CHI3L1 (chitinase 3 like 1)
Diseases named in the same sentence as CHI3L1 in open-access papers (continued):
Sharing a sentence is not in itself a finding about the gene and the disease.
glioblastoma (continued). "CHI3L1 is a marker for the mesenchymal subtype of glioblastoma and is related to extracellular-signal-regulated kinases and protein kinase B phosphorylation." (PMID 29467925, 2018). "PTX3, FAPB7, POSTN, and PDPN are associated with increased glioma invasion, and both PDPN and CHI3L1 reportedly contribute to radio-resistance in glioblastoma." (PMID 29523123, 2018). "CHI3L1 (Chitinase-3-like protein 1) is one of the most overexpressed genes in glioblastomas, relative to normal brain and low-grade gliomas." (PMID 29467925, 2018). "Blockade of CHI3L1 activity or expression suppressed tumor vasculature in glioblastoma xenografted animals." (PMID 30165890, 2018). "The function of KLRC3 is not restricted to its effect on radiosensitivity but also concern glioblastoma self‐renewal property which is significantly decreased compared to CHI3L1 extinction." (PMID 27641066, 2017). "We have previously reported that CHI3L1 was overexpressed in undifferentiated glioblastoma stem cells (GSC) from U87‐MG and U251 cell lines and in gliomaspheres from primary cell culture derived from patients." (PMID 27641066, 2017). "VEGFC (p < 0.001), HGF (p = 0.014), and CHI3L1 (p = 0.043) RNA expression levels were significantly different between the five glioblastoma locations." (PMID 26637806, 2016). "Multiple comparison analysis showed significantly higher CHI3L1 mRNA expression in glioblastoma (grade IV) cohort compared with II and III grade gliomas (p < 0.001)." (PMID 27121858, 2016). "It should be noted that these data are in the line with gene mRNA expression distribution across tumor grade – higher CHI3L1 expression was intrinsic for glioblastoma tissue." (PMID 27121858, 2016). "Despite grade I glioma specimen showed similar CHI3L1 expression profile to glioblastoma specimen Kaplan-Meier curves strongly separate patient with different expression level to diverse survival groups." (PMID 27121858, 2016). "We demonstrated that mRNA expression of CHI3L1 was evidently higher in glioblastoma than in lower grade glioma tissues." (PMID 27121858, 2016). "Recently, a number of gene expression array studies have identified CHI3L1 to be one of the most overexpressed genes in glioblastoma when compared to low-grade glioma and normal brain, but most of them were carried out with small sample number." (PMID 27121858, 2016). "When CHI3L1 expression of a glioblastoma cell line was inhibited, VEGF production was reduced but blockade of VEGF induced the expression of CHI3L1." (PMID 26425658, 2015). "This review focuses on recent discoveries that the angiogenic factor YKL-40 (CHI3L1) acts on glioblastoma-stem like cells (GSCs) to drive the formation of two major forms of tumor vascularization: angiogenesis and vasculogenic mimicry (VM)." (PMID 26439689, 2015). "The proinflammatory cytokines, such as IL-1, TNF-α, and IL-6, modulate CHI3L1 expression in chondrocytes, macrophages, and also glioblastoma cells." (PMID 26425658, 2015). "Levels of circulating CHI3L1 are increased in many malignancies, including cancers involving the lung, prostate, colon, rectum, ovary, kidney, breast, glioblastomas, and malignant melanoma." (PMID 26425658, 2015). "YKL-40, a chitinase homolog also called human cartilage glycoprotein 39 or chitinase 3-like 1, is one the most promising serum markers for glioblastoma currently in development." (PMID 24809021, 2014). "Of note, hypoxia stimulated CHI3L1 production in a glioblastoma cell line, which promotes cell survival." (PMID 25047113, 2014). "This immature neural profile was associated in the four TSCs cultures we tested with high-transcript levels of molecules normally present in mesenchymal cells including CHI3L1/YKL40, which is also known as a marker of adult glioblastoma aggressiveness." (PMID 21297991, 2011). "In glioblastoma (GBM), where necrosis is a characteristic, both CHI3L1 expression and necrosis are associated with poor prognosis." (PMID 18781180, 2008).
glioblastoma (continued). "This cluster contained several genes well-known to be overexpressed in glioblastomas (IGFBP2, CHI3L1) and markers of glioblastoma cancer stem cells as well (CD133, IQGAP1)." (PMID 18492260, 2008). "The expression of CHI3L1 in glioblastoma cells may be precisely regulated by an adverse environment, such as nutrient depletion or anti-tumour treatment." (PMID 42062601, 2026). "The need for innovative therapeutic approaches is more critical than ever, and CHI3L1 is at the leading edge of potential targets that could revolutionize the management of glioblastoma and other malignant brain tumors." (PMID 39827337, 2025). "Interestingly, Francescone’s team observed an increased expression of CHI3L1 in U-87 MG glioblastoma cells after γ-irradiation, leading to protection against cell death." (PMID 39399677, 2024). "In glioblastoma, CHI3L1 regulates tumorigenesis by disrupting the guidance pathway." (PMID 37887529, 2023). "IL-13Rα2 is the most common therapeutic target in glioma; Recent studies have shown that IL-13Rα2 can signal through the AP-1 pathway where it cooperates with other molecules, such as chitinase 3-like 1 (CHI3L1) and epidermal growth factor receptor variant III (EGFRvIII), in glioblastoma." (PMID 37158824, 2023). "CHI3L1 is highly expressed in glioblastoma and is related to poor patient prognosis." (PMID 37759870, 2023). "In addition, in various cancer cell lines, including A549 lung cancer cells, A172 glioblastoma cells, U-2 OS osteosarcoma cells, and Hep3B liver cancer cells, a novel localization of CHI3L1 was identified." (PMID 37215572, 2023). "Reactive CD274+ astrocytes secrete the glycoprotein chitinase 3 like 1 (CHI3L1) for promoting a subtype-shift of glioblastoma towards the mesenchymal phenotype, driving mitogen-activated protein kinases (MAPK) signaling as well as high proliferation rate and migration." (PMID 33804873, 2021). "It was also reported CHI3L1 was related to immune infiltration in breast cancer and glioblastoma." (PMID 33937022, 2021). "Since CHI3L1 is known to be overexpressed in glioblastomas, we wanted to assess whether CHI3L1 was globally expressed in glioblastoma tumor cells." (PMID 31561550, 2019). "Previously, we observed in glioblastoma cell lines that CHI3L1 might be a cancer stem cell biomarker in glioma, based on glycosylation-related gene expression analysis, and may be a potential biomarker of aggressiveness." (PMID 30991699, 2019). "CHI3L1 is more highly expressed in glioblastoma than in normal brain." (PMID 30991699, 2019). "Next we decided to examine whether the increase of CHI3L1 mRNA level in glioblastomas is due to the promoter methylation of the CHI3L1 gene." (PMID 27121858, 2016). "In particular, transcriptomic analyses showed a mesenchymal profile for periventricular glioblastoma stem-like cell line, with overexpression of VEGFC and CHI3L1 and a proneural profile for cortical glioblastoma stem-like cell line with overexpression of PROM1, DLL3, and BCAN." (PMID 26637806, 2016). "Our findings propose that mRNA expression values of CHI3L1, could be useful, not only for glioblastoma, but for lower grade astrocytoma diagnosis and prognosis too." (PMID 27121858, 2016). "In addition, CHI3L1 (chitinase 3-like 1), also known as BRP-39/HCGP39/YKL-40, is considered a reliable gene expression marker for the mesenchymal subclass and local invasiveness of glioblastomas." (PMID 25893706, 2015). "CHI3L1 protein overexpression and high microvascular density (MVD) were significantly associated with tumor relapse and an unfavorable overall survival in NSCLC, hepatocellular carcinoma, glioblastoma, cervical and renal cancer." (PMID 26425658, 2015). "This trend is consistent with reports that Chi3l1/Ykl-40 was highly overexpressed in glioblastoma relative to nonneoplastic brain and that Ykl-40 is associated with poorer response to radiation and shorter lifetime survival in glioblastoma." (PMID 21649900, 2011).
glioblastoma (continued). "Additionally, we have learned in previous studies that CHI3L1 (the homologous gene of CHI3L2) may be used as an immunomodulatory factor to affect the therapeutic efficacy of PI3K/AKT-based pathway inhibitors in glioblastoma." (PMID 33937022, 2021). "Similarly, the expression of mesenchymal subtype markers, such as FN, Vim, and YKL-40 (a marker for the mesenchymal subtype of glioblastoma, also known as Chitinase-3-like protein 1, CHI3L1), was induced by irradiation and suppressed by blocking CD44 expression." (PMID 34681583, 2021). "Consistent with our findings, both CHI3L1 and CHI3L2 have been shown to drive proliferation in a variety of human cell types in addition to being associated with numerous chronic inflammatory diseases and cancers including glioblastoma, non-small cell lung cancer and colon cancer." (PMID 33370287, 2020). "We have previously shown that CHI3L1 is overexpressed in undifferentiated U87-MG cells and in neurosphere-forming glioblastoma stem cells, isolated from GBM patients." (PMID 27385098, 2016). "There are data that suggest that CHI3L1 expression could be a prognostic predictor of glioblastoma." (PMID 27801851, 2016). "As SCLC is just an example of a highly invasive cancer the proposed model may hold true for other tumor entities, especially in the light of several similar features observed in invasive glioblastoma such as CHI3L1-positivity and recruitment of myloid-derived suppressor cells." (PMID 26425658, 2015). "In this context, the particular potential of CHI3L1 inhibition could be considered in glioblastoma multiforme (GBM), whose tumors exhibit high levels of angiogenesis and increased CHI3L1 expression." (PMID 39399677, 2024). "Lou demonstrated that the NF-kB inhibitor zeta (NFKBIZ) was a downstream target of NUDT21, and that MES recognition genes CHI3L1 and FN1 were differentially regulated in glioblastoma cells." (PMID 38349866, 2024). "Patients with various cancers, including breast, gastrointestinal, liver, prostate, brain, endometrial, and lung cancers, as well as astrocytoma and glioblastoma, have elevated levels of CHI3L1(YKL40) in their serum." (PMID 38543093, 2024). "Recently, it was reported that chitinase 3-like 1 (Chi3l1) binds to CD44 and induces the phosphorylation of β-catenin at Ser552 by Akt in glioblastomas and TANK-binding kinase 1 (TBK1) in cholangiocarcinomas, leading to its nuclear translocation." (PMID 38136210, 2023). "To validate our analysis, we measured the expression of CHI3L1 and EMP3 in normal and low-grade glioma cells and glioblastomas." (PMID 37887529, 2023). "Reactive astrocytes of the tumor environment released CHI3L1, which drives MAPK and AKT signaling in glioblastoma via stimulation of IL13Rα2." (PMID 31561550, 2019). "For example, both glutamate decarboxylase 1 (GAD1) and Chitinase 3 Like 1 (CHI3L1/YKL-40) have been recently identified as targets of Notch inhibitors (alpha secretase and gamma secretase inhibitors) in treating glioblastoma stem cells." (PMID 30626092, 2019). "To determine the putative role of CHI3L1, KLRC3 and PRUNE2 genes in glioblastoma aggressiveness, we have assessed the three shRNA cell lines tumourigenic potential." (PMID 27641066, 2017). "Three genes named CHI3L1,KLRC3 and PRUNE2 were found overexpressed in glioblastoma undifferentiated cells (related to CSC) compared to the differentiated ones." (PMID 27641066, 2017). "In the present study, the effect of KLRC3 extinction is compared to those of the two other genes CHI3L1 and PRUNE2 in a human glioblastoma cell line." (PMID 27641066, 2017). "To analyse the role of KLRC3, CHI3L1 and PRUNE2 genes in the migration ability of glioblastoma cells we used a matrigel invasion chamber system." (PMID 27641066, 2017). "Castells and colleagues reported that the expression values from only four transcripts (CHI3L1, LDHA, LGALS1, and IGFBP3) were able to distinguish two survival groups in Glioblastoma." (PMID 27121858, 2016).
glioblastoma (continued). "YKL-40 coded by CHI3L1 gene, a member of the chitinase-like glycoprotein family, is involved in growth and survival of glioblastoma cells." (PMID 27385098, 2016). "In this study, we correlated glioblastoma locations with the expression of five mesenchymal genes (VEGFC and its receptor FLT4, HGF and its receptor MET, and CHI3L1) and five proneural genes (PROM1, NOTCH1, DLL3, PDGFRA, and BCAN)." (PMID 26637806, 2016). "This, in combination with analysis of glioblastoma formalin-fixed paraffin-embedded tissue samples identified a nine-gene signature including IGFBP-2, chitinase-3-like protein 1 (CHI3L1)/YKL-40, galectin 3 (LGALS3) and OLIG2 that was predictive of worse clinical outcomes." (PMID 40429889, 2025). "Besides QPCT, chitinase-3-like 1 protein (CH3L1), which we also found to belong to our gene signature, has been demonstrated to modulate an immunosuppressive microenvironment in glioblastoma by reprogramming TAMs to M2-like phenotypes." (PMID 37370678, 2023). "Furthermore, CHI3L1 and VEGF synergistically promote angiogenesis and malignancy in glioblastoma and melanoma 9-11." (PMID 34987649, 2022). "While CHI3L1 significantly impacts the survival of glioblastoma patients, TMEM219 did not affect overall survival." (PMID 31561550, 2019). "Potential binding partners of CHI3L1 have been previously identified, but clear evidence regarding the presence of a receptor present in glioblastoma cells has not been presented." (PMID 31561550, 2019). "Chitinase 3 Like 1 (CHI3L1/YKL-40) was also reported previously to be prognostic to glioma patient survival and involved in the angiogenesis, radioresistance, and progression of glioblastoma in vivo." (PMID 30626092, 2019). "Phospho-c-Jun activation by Anisomycin treatment in primary glioblastoma-derived cells attenuates the aggressive features of mesenchymal glioblastomas and leads to promoter methylation and downregulation of key mesenchymal genes (CD44, MMP9 and CHI3L1)." (PMID 28036297, 2017). "To further characterize gene expression in the Ad-GSCs and Sp-GSCs tumor xenografts, we examined the expression of genes previously defined to be characteristic of the Classical (FGFR3, PDFA, EGFR, AKT-2 and Nestin) and Mesenchymal (CHI3L1, TRADD, NF1, RelB and CASP4) glioblastoma subtypes." (PMID 25955030, 2015). "As it was shown recently, CHI3L1 expression is absent in subset of glioblastomas termed “proneural”, which comprise up to 30% of all glioblastomas, due to promoter hypermethylation." (PMID 23675241, 2011). "Although silencing of CHI3L1, KLRC3 and PRUNE2 decrease cell proliferation, migration, clonogenicity and tumourigenesis, our results demonstrate that KLRC3 is of prime importance for glioblastoma cells aggressiveness and their ability to promote cancer progression." (PMID 27641066, 2017). "Based on our previous study describing an overexpression of three glycosylation‐related genes, KLRC3, CHI3L1 and PRUNE2 in glioblastomas undifferentiated cells related to CSC, we assessed whether these genes are closely linked to glioma tumourigenesis mechanisms." (PMID 27641066, 2017). "There are data that, CHI3L1 expression could be a prognostic predictor of glioblastoma, although other studies have not supported this role." (PMID 27121858, 2016). "In addition, focused microarray analysis of glyco-gene expression in human glioblastomas identified various genes that are more highly expressed in gliomas relative to normal brain, including O-fucosyltransferase 1 (POFUT1) and chitinase 3-like 1 (CHI3L1)." (PMID 26132161, 2015). "Besides the classical targets VEGF, MMP-9 and PD-1, CHI3L1 constitutes a new possibly drugable molecule to retard down dissemination of SCLC cells, which may be similarly relevant for glioblastoma and other tumor entities." (PMID 26425658, 2015).
glioblastoma (continued). "This article analyzes for the first time the effects of G721–0282, a CHI3L1 inhibitor, on the expression of proteins involved in intercellular junctions, such as E-cadherin, N-cadherin and VCAM-1, in GBM spheroids composed of glioblastoma U-87 MG cells, macrophages and HMEC-1 endothelial cells." (PMID 39399677, 2024). "The relationship between IDH status and NTRK2 or CHI3L1 has not yet been studied in grade II and III tumors and was only reported for glioblastoma." (PMID 30991699, 2019).